IL17A (interleukin 17A)
Diseases named in the same sentence as IL17A in open-access papers (continued):
Sharing a sentence is not in itself a finding about the gene and the disease.
breast cancer (continued). "We previously demonstrated that breast cancer-infiltrating immunosuppressive macrophages released a large amount of IL17A, especially when treated with taxan." (PMID 33802061, 2021). "IL-17A for example, has been shown to promote proliferation, migration and invasion of several breast cancer cell lines." (PMID 33809315, 2021). "Along these lines, high expression of IL-17A-expressing cells is a strong indicator of disease progression in patients with head and neck cancers and of poor prognosis in those with breast cancer." (PMID 33922465, 2021). "Since IL-17A, IL-17F, and IL-17C are initiators of IL-17 signal transduction, whereas IL-17E suppresses Th17 cell responses, ER downregulates IL-17 signal transduction in breast cancer by differentially regulating the expression of IL-17 cytokines." (PMID 33102239, 2020). "Several studies have found excess expression of IL-17A in various tumor tissues, including prostate cancer, colorectal cancer, breast cancer, and gastric cancer." (PMID 32616024, 2020). "The PD-1 and PD-L1 levels were compared between breast cancer samples with different ER statuses and IL-17A/IL-17F expression levels." (PMID 33102239, 2020). "Collectively, our data highlight the pleiotropic effects of IL-17A in breast cancer and support the use of therapeutic modalities that deplete MDSCs in IL-17A-enriched tumors." (PMID 32770025, 2020). "Many studies suggest that an increased level of IL-17A in breast cancer tissue is related to ER-negative status or the triple-negative subtype." (PMID 33102239, 2020). "It has been found in vitro and through animal experiments that IL-17A promotes tumor growth, metastasis, and microangiogenesis through a variety of mechanisms in breast cancer." (PMID 33102239, 2020). "This indicates that the downregulation of IL-17A and IL-17F signal transduction is a possible mechanism involved in the decrease in PD-1/PD-L1 expression in breast cancer with a high level of ER expression." (PMID 33102239, 2020). "Increased expression of PD-1/PD-L1 was associated with ER-negative status, IL-17A-positive status, IL-17F-positive status, and upregulation of IL-17 signaling pathway-related genes in breast cancer." (PMID 33102239, 2020). "We selected a set of five inflammatory factors (IL1A, IL6, IL17A, IFNβ, and NFĸB) that were found to be overexpressed in aggressive breast carcinomas." (PMID 33396463, 2020). "Collectively, our study demonstrates that MDSC depletion is an effective and practical approach for treating IL-17A-enriched mammary carcinomas." (PMID 32770025, 2020). "In breast cancer, elevated IL-17A expression results in polarization of neutrophils which suppress CTLs and eventually, promoting metastases." (PMID 31159823, 2019). "It was demonstrated that IL-17A was over expressed in cervical cancer, breast cancer, hepatocellular carcinoma, non-small cell lung cancer, and pancreatic cancer." (PMID 31064389, 2019). "The Th17 subset primarily produces IL-17A to promote proliferation, metastasis, and drug resistance of breast carcinoma." (PMID 31145753, 2019). "To this end, we developed HDN-TIMP2,V3: a novel bi-specific heterodimer that successfully inhibits both MMP-9 activation and IL-17A-induced cytokine secretion to synergistically inhibit the invasion of breast cancer cells." (PMID 29983876, 2018). "Our group previously reported that TAMs in a spontaneous model of breast cancer produce IL-1β, which stimulates the expression of IL-17 (also known as IL-17A) from γδ T cells." (PMID 30355585, 2018). "Whereas most MAIT cells within the C12 breast duct-derived MAIT line produced both IFN-γ and IL-17A in response to PMA/ionomycin stimulation, their response to the breast carcinoma cells was nearly exclusively limited to IL-17A production." (PMID 30208917, 2018). "It has been reported that recombinant IL-17A recruits the MAPK pathway by upregulating phosphorylated ERK1/2 in human breast cancer cell lines." (PMID 27935862, 2017).
breast cancer (continued). "We checked serum IL-17A levels in 122 breast cancer patients and found that IL-17A levels correlated with ER/PR-negative status, but not with HER2 expression and clinical tumor stage (p < 0.05)." (PMID 27935862, 2017). "Our next step was to further assess the molecular signaling after stimulation of human breast cancer cell lines with IL-17A and IL-17E." (PMID 27589729, 2016). "Nevertheless, our team also observed that human breast cancer cell lines expressed IL-17RA and IL-17RC, and stimulation with IL-17A recruited the MAPK pathway by upregulating phosphorylated ERK1/2 as reported in previous studies." (PMID 27589729, 2016). "Here, we investigated the action of IL-17A and IL-17E on breast cancer cell lines and cell signaling events induced after recruitment of IL-17RA/IL-17RC or IL-17RA/IL-17RB receptors." (PMID 26154409, 2015). "It was reported that IL-17A and IL-17B neutralizing antibody treatments led to decreased breast cancer growth in mice." (PMID 26154409, 2015). "In contrast, we observed a consistent increase of cyclin E in the primary breast cancer cell line IJG-1731 when cultured with either IL-17A or IL-17E." (PMID 26154409, 2015). "In the present study, we aimed to identify in breast cancer cells the signaling pathways recruited following IL-17A and IL-17E cytokine stimulation." (PMID 26154409, 2015). "In the present study we report that IL-17A and IL-17E receptors subunits mRNA expressions are upregulated in breast cancers versus normal samples." (PMID 26154409, 2015). "Recently, interleukin-17A (IL-17A) has been also frequently observed in many cancers such as ovarian cancer, breast cancer, gastric cancer, and hepatocellular carcinoma." (PMID 25244643, 2014). "Recently, IL-17A has been also frequently found in many cancers such as ovarian cancer, breast cancer, gastric cancer, and hepatocellular carcinoma." (PMID 25250801, 2014). "Several studies have found overexpressing of IL-17A in various tumor tissues, including multiple myeloma, ovarian cancers, gastric cancer and breast cancer." (PMID 22461912, 2012). "Recently IL-17A has been also frequently detected in many cancers such as ovarian cancer, breast cancer and gastric cancer." (PMID 21760911, 2011). "Similarly, M. globosa colonization promotes breast cancer progression by inducing interleukin 17A-driven M2 macrophage polarization." (PMID 41510169, 2026). "Specifically, the IL-17A/NF-κB/MMPs axis promotes breast cancer bone metastasis." (PMID 41597595, 2025). "A recent study found that M. globosa colonization in breast tissue promotes the production of IL-17A by breast cancer cells, modulates NF-κB activity, and increases the expression of IL-6 and cyclooxygenase-2 (COX-2), thereby stimulating the proliferation of mice BC cells." (PMID 41597595, 2025). "Of note, repolarizing CX3CR1+ TAMs toward an immunostimulatory configuration with a monoclonal antibody targeting colony stimulating factor 1 receptor (CSF1R) ameliorated the activity of P+T against M/D-driven mammary carcinoma, to a magnitude similar to IL17A neutralization." (PMID 40662849, 2025). "From the calculation of the association of IL-17A rs3748067 with breast cancer, it is found that no genotype or allele showed a statistically significant association (p>0.05)." (PMID 38816694, 2024). "Numerous studies have reported a higher expression of IL-17A in tumor cells, including breast cancer, colorectal carcinoma, gastric carcinoma, hepatocellular carcinoma, ovarian cancer, medulloblastoma, pancreatic cancer, non-small-cell lung cancer, and thyroid cancer." (PMID 38816694, 2024). "Combining IL-17A neutralization with immune checkpoint inhibitors (ICIs) has been shown to not only maintain the anti-tumor efficacy of ICIs but also to inhibit PD-L1 expression in breast cancer cells." (PMID 39906741, 2024). "This study concludes that rs3748067 polymorphism in the IL-17A gene is associated with cervical cancer, not breast cancer in Bangladeshi patients." (PMID 38816694, 2024).
breast cancer (continued). "Moreover, the IL-17A/macrophages axis plays a key role in mechanisms involved in the M. globosa-induced breast cancer acceleration from the tumor immune microenvironment perspective." (PMID 39235230, 2024). "The role of IL-17A blockade in breast cancer treatment is yet to be examined." (PMID 37427128, 2023). "The evidence suggested that targeting and reprogramming multiple downstream signaling pathways of IL-17A may be an essential complementary option to promote the efficacy of conventional chemotherapy to treat breast cancer metastasis." (PMID 36993955, 2023). "Thus, in the animal model experiment, IL-17A is considerably a therapeutic target during the chemotherapeutic management of breast cancer since its inhibition decreases cancer progression, migration, and distant metastasis." (PMID 36993955, 2023). "Pesticide exposure also augmented IL-17A in eutrophic breast cancer patients." (PMID 37942322, 2023). "We found that genetic deletion of γδ T cells elicits responsiveness to anti–PD-1 and anti–TIM-3 immunotherapy in a mammary tumor model that is refractory to T cell checkpoint inhibitors, indicating that IL-17A–producing γδ T cells instigate resistance to immunotherapy." (PMID 36480166, 2023). "The results support the fact that the immune response in early breast cancer is mediated, among other, by cells that secrete IL-17A, and that after the removal of the tumor, even though the reaction mediated by IL-17A subsides, serum IL-17A level remains elevated compared to the healthy population." (PMID 37427128, 2023). "We used a mouse model of breast cancer in which the γδ T cell–IL-17A–neutrophil axis is established: the K14-Cre;Brca1F/F;Trp53F/F (KB1P) model of triple negative breast cancer, which develops invasive ductal carcinoma in one or more mammary glands at around 8 mo of age." (PMID 36480166, 2023). "In accordance with previous research, data analysis from this research revealed a significantly higher serum concentration of IL-17A in the serum of women with early breast cancer at diagnosis, but also after surgical removal of the tumor during adjuvant treatment compared to the control group." (PMID 37427128, 2023). "Breast cancer growth, migration, angiogenesis, and invasiveness are further enhanced by IL-17A." (PMID 36140808, 2022). "Consistently, it has been reported that the expression of IL-17A correlates with vascular density in the tumor tissues of various cancers such as colon cancer, gastric carcinoma, hepatocellular carcinoma, lung cancer, pancreatic cancer, and breast cancer." (PMID 34885241, 2021). "Indeed, primary growth and metastasis of B16-F10 melanoma and 4T1 breast cancer was reduced in mice depleted of IL-17A by host knockout or antibody neutralization, respectively." (PMID 33922465, 2021). "Though, based on sequence homology IL-17F may share many functions with IL-17A in hosts with skin or breast cancers." (PMID 33922465, 2021). "Combining anti-VEGFR2 therapy with immunotherapy such as IL17A, PD-1 or Ly-6G mAb therapy, which targeting the immunomodulatory axis of “γδT17 cells-N2 neutrophils” in vivo, showed promising therapeutic effects in breast cancer treatment." (PMID 34721375, 2021). "In addition, breast cancer patients with high intra-tumoral IL-17A expression have been shown to have strong intra-tumoral Th1 responses." (PMID 32770025, 2020). "In addition to those genes that encode downstream products of IL-17A/IL-17F signaling transduction, the expression levels of IFNG, FOS, FOSB1, and FOSL1 were also found to be associated with ER status in breast cancer." (PMID 33102239, 2020). "In addition, notably, IL-17 family plays an important role in the specific organ metastasis of breast cancer: one reported mouse model manifests that IL-17A leads metastases to the lungs and bones; IL-17E is proposed to be related to lung metastasis formation." (PMID 33378415, 2020).
breast cancer (continued). "This suggests that ER downregulates the intensity of the response to IL-17A/IL-17F signaling in breast cancer, which might result from reduced IL-17A/IL-17F levels and decreased Th17 cell infiltration." (PMID 33102239, 2020). "In addition to IL-17A, many other chemokines are involved in breast cancer progression via paracrine regulation." (PMID 32415115, 2020). "Furthermore, the impact of tumor-derived IL-17A in host immune response and tumor growth was examined using murine TNBC 4T1 mammary carcinoma cells transduced with an adenoviral vector expressing IL-17A (AdIL-17A) or control vector (Addl)." (PMID 32770025, 2020). "In addition, IL-17A stimulates the expression of the MMP-9 mRNA, and IL-17A-dependent invasion of breast cancer cells can be inhibited by MMP-9 inhibitors." (PMID 29983876, 2018). "However, we found that breast MAIT cells that were exposed to E. coli-pulsed breast carcinoma cells produced only IL-17A and TNF-α." (PMID 30208917, 2018). "Thus, our study established a pro-tumor role of IL-17A in promoting tumor immune escape and supports the development of a novel cytokine immunotherapy against breast cancer." (PMID 27935862, 2017). "As we previously reported for IL-17A, IL-17B present in the tumor microenvironment could be an important cancer cell survival factor and a mediator of therapy resistance in breast cancer." (PMID 29371916, 2017). "To examine the role of IL-17A/IL-17R in controlling cancer cell proliferation, we selected two well-characterized tumor cell lines, B16 melanoma and 4T1 mammary carcinoma, for our study and created IL-17RCKD clones using retroviral shRNA constructs alone with pSMP control vector." (PMID 28562353, 2017). "Nevertheless, the results described herein, together with those of our previous report, show the importance of IL-17A in pro-oncogenic signaling in breast cancer and are indicative of the key roles played by IL-17 family members within the TNBC microenvironment." (PMID 27462789, 2016). "Investigation of the molecular signaling following stimulation of human breast cancer cell lines with IL-17A and IL-17E showed that both cytokines induced the phosphorylation of c-RAF, ERK1/2 and p70 S6 Kinase were involved in the proliferation and survival of tumor cells." (PMID 26154409, 2015). "Taking together the findings reported here suggest that IL-17A and IL-17E are expressed and active in breast cancer and may participate to tumorogenesis." (PMID 26154409, 2015). "Furthermore, the three IL-17R subunits, corresponding to the IL-17E (IL17RA/RB) and IL-17A (IL17 RA/RC) receptors, were highly upregulated in tumor versus normal samples, suggesting that IL-17E as IL-17A signaling is potentially active in human breast cancer." (PMID 26154409, 2015). "Previous research found that IL-17A could promote the migration and invasion abilities of human breast cancer and hepatocellular carcinoma cells." (PMID 25250801, 2014). "Our results suggested that SNPs in IL-17A but not IL-17F were associated with the risk of breast cancer." (PMID 22461912, 2012). "Although the significance of IL-17A and IL-17F in the pathogenesis of breast cancer is unclear, we hypothesized that both cytokines may affect the development of breast cancer, either coordinately or independently." (PMID 22461912, 2012). "Only the frequencies of the AA genotype and the A allele in rs2275913, located at position −197 from the starting codon of the IL-17A gene, were statistical significant higher in breast cancer patients than in controls (P = 0.0016 and P = 0.0029, respectively)." (PMID 22461912, 2012). "And IL-17A was also proved to can promote the motility of breast cancer cells in another study." (PMID 21760911, 2011). "Furthermore, we are presently investigating the expression of the two key IL-17 receptor chains on breast cancer cells, RA and RC, which heterodimerise to mediate signalling following binding of IL-17A and IL-17F." (PMID 19014637, 2008).
breast cancer (continued). "Our study summarizes that rs3748067 polymorphism in the IL-17A gene may be associated with cervical cancer but not breast cancer in Bangladeshi patients." (PMID 38816694, 2024). "It was also noticed in our study that transcripts encoding IL-17A and IL-17F in the majority of samples and transcripts encoding IL-17C and IL-17E in half of the samples were absent according to TCGA Breast Cancer dataset, which made the quantitative analysis difficult." (PMID 33102239, 2020). "IL-17C is similar to IL-17A in promoting the expression of inflammatory cytokines and antibacterial peptides, whereas it is mainly derived from epithelial cells, which may explain why more positive samples with IL-17C expression were observed than those with IL-17A expression in breast cancer." (PMID 33102239, 2020). "In addition, the expression of the five signature cytokines is negatively correlated with tumor purity in breast cancer, especially for IL-17A, IL-21, and IL-26, which indicates that these cytokines are mainly derived from immune cells such as Th17 cells rather than tumor cells." (PMID 33102239, 2020). "In addition, IL-17A-dependent invasion of breast cancer cells can be inhibited by MMP-9 inhibitors." (PMID 29983876, 2018). "Previous studies have shown that the IL-17A-mediated invasion of breast cancer cells can be inhibited by selective antagonists of the matrix metalloproteinase 9 (MMP-9), suggesting that the cross-talk between IL-17A and MMP-9 may promote cancer invasiveness and metastasis." (PMID 29983876, 2018). "Thus, it will be of great interest to determine whether IL-17A-producing MAIT cells are selectively expanded within breast carcinoma tissue, as has been observed recently for colon carcinomas." (PMID 30208917, 2018). "Furthermore, IL-17A and IL-17E (IL-25) were involved in proliferation and survival of human breast cancer cell lines T47D and MCF7 as well as primary breast cancer biopsy cells IJG1731 and thereby promoted their resistance to the antimitotic chemotherapy agent docetaxel." (PMID 26783383, 2015). "Thus, our results support the hypothesis that both IL-17A and IL-17E are involved in breast cancer progression by activating common signaling cascade end point despite the fact these cytokines trigger distinct receptors." (PMID 26154409, 2015). "In addition, it was demonstrated that rs2275913 in IL17A but not IL17F was associated with the risk of breast cancer." (PMID 23049595, 2012). "Conversely, in breast cancer, mast cells recruited and activated by tumor cells can induce transcriptional changes in genes such as SPP1, PDCD1, IL17A, TGFB1, KITLG, and IFNG, leading to anti-tumor effects." (PMID 40495762, 2025). "Overall, this review article emphasizes IL-17A and its intermediate signaling molecules, such as ERK1/2, NF-kB, MMPs, and VEGF, as potential molecular targets for the prevention and treatment of breast cancer." (PMID 36993955, 2023). "With a significant increase in IL17A, IL17E, and IL27p28 levels, the circulatory cytokine milieu thus appears to be favorable for breast cancer progression." (PMID 37503343, 2023). "In mice with EO771 breast cancer, the abundances of CXCL1 in the diseased lungs of Ifng−/− mice and Il17a/Il17f−/− mice were 6% and 18% of that in the diseased lungs of mock C57 mice." (PMID 37553342, 2023). "The relation between IL-17A and its downstream MMP activity and breast cancer metastasis through MAPK and NF-Kb suggests the possibility of various strategies connected with blocking these checkpoints and kinase enzyme activity." (PMID 36993955, 2023). "Previously, we have shown the immunomodulatory effect of cisplatin in triple negative murine breast cancer model reducing the emergence of splenic CD44+, IL-17A+ myeloid suppressor cells." (PMID 37901220, 2023). "IL-17A promotes ERK1/2 phosphorylation and p38 MAPK activation, which in turn promotes breast cancer cell proliferation, migration, and tissue invasion." (PMID 36140808, 2022).